IL6 (interleukin 6)
Diseases named in the same sentence as IL6 in open-access papers (continued):
Sharing a sentence is not in itself a finding about the gene and the disease.
infection (continued). "Similarly, it was tempting to associate the early IL-6 signaling in the liver with the parasite clearance and the subsequent elicitation and expansion of CD4 and CD8+ cells under the control of IL-6 shown to protect against infections caused by several pathogens." (PMID 33329563, 2020). "After infection for 12 h to 24 h, the expressions of IFN-α, IFN-β, TNF-α, IL-6, IL-8, and IL-12 began to increase continuously, and the levels of transcriptions of these inflammatory factors peaked at 24 h." (PMID 32133381, 2020). "The physically normal IL-6 and TNF-α levels in the blood of healthy people have the effects of anti-infection and immune function enhancement, but too much of them can damage the tissue." (PMID 32089647, 2020). "The patients with higher infection index (such as CRP, PCT, ESR, SAA, IL-6) were prescript antibiotics for 5–7 days in addition." (PMID 32208917, 2020). "The levels of inflammatory markers such as TNF-α, IL-6, and MCP-1, is all correlated with the severity of infection." (PMID 32434424, 2020). "For example, one study showed that plasma levels of IL-2, IL-6, IL-8, IL-10, and TNF-α, were found to be higher in patients with severe infection than those with mild to moderate infection." (PMID 32984253, 2020). "Infection with RV1B induced a marked increase in IL-8 (17-fold over untreated), IL-6 (7-fold) and CCL5 (33-fold)." (PMID 32117246, 2020). "The release of chemokines can also stimulate the expression of inflammatory cytokines, such as IL-1, IL-6, and TNF-α, which can repair infection or tissue damage." (PMID 32215271, 2020). "IL-6 is the key cytokine triggering increased liver production of acute-phase proteins (APPs) such as C-reactive protein (CRP) and fibrinogen, causing a hypercoagulable disease that is characterized by thrombotic and embolic events, and may predict severity of infection." (PMID 32635302, 2020). "The lung homogenates of WT and AhR−/− mice were collected after 96 h, 2 and 10 weeks of infection and used to evaluate the presence of cytokines (IL-12, TNF-α, IL-1β, IL-6, IL-23, IL-2, IFN-γ, IL-4, IL-17, IL-22, TGF-β, IL-10, IL-27, and IL-35)." (PMID 32647342, 2020). "Results from qRT-PCR analysis showed that the expression of Ifnb, Il6, and Ccl5 in the hearts and brains of Rnf115−/− mice was higher than that of wild-type littermates at day 4 after EMCV infection." (PMID 33139700, 2020). "IL-6 was significantly upregulated at multiple time points in pH1N1-MRSA infections, and at 24 h in pH1N1-alone infections." (PMID 33202895, 2020). "Our results show that the relative transcription levels of IL-17A, IL-22, IL-6, IL-1β, IFN-γ, and TNF-α increased at 5 and 12 days post H9N2 AIV infection, and these results are consistent with our previous research results and other reports." (PMID 33294434, 2020). "We found that overexpression of TRIM35 in THP-1 cells significantly enhanced transcription of IFNB1, TNFα, IL6, and ISG56 after infection with SeV." (PMID 32562145, 2020). "Proinflammatory IL-1β, IL-6, and tumor necrosis factor alpha (TNF-α) levels were markedly increased upon any infection compared to mock control and were higher during C. glabrata or C. parapsilosis infections." (PMID 33024045, 2020). "The difference is that, on day 0 post-infection, intraperitoneal injection of CoA can obviously induce the expressions of TNF-α, IL-1β, IL-6, and IFN-γ in the lungs, but oral administration of valine only stimulates IFN-γ." (PMID 32345342, 2020). "These genes’ expressions were decreased on day 33; however, compared with mock infection, IFNα, Rig-I, OAS-1, IRF7, MxA, and IL6 were also expressed at a statistically significant higher level." (PMID 32121148, 2020). "The production of IL-6 and TNF-α increased at 16 h (16.05% ± 2.51% and 15.17% ± 1.21%, respectively), but declined at 20 h post-infection (5.87% ± 0.64% and 7.92% ± 0.88%, respectively)." (PMID 33261178, 2020).
infection (continued). "The mRNA levels of IL1β, IL6, TNF-α and IFN-β in porcine intestinal epithelial cells infected with SDSX16-P10 strain were much lower than SDSX16-P75 at 18 h post-infection (hpi)." (PMID 32244640, 2020). "Ms_YrbE3A infection resulted in the highest concentrations of pro-inflammatory cytokines, including TNF-α, IL-1β, IL-6, MCP-1, IL-1α, IL-12p70, and IFN-γ, in the lungs at 2 d PI and later decreasing rapidly from 4 to 21 d PI." (PMID 32316659, 2020). "In contrast, infection with MCMV down-regulated the expression of IL-10 and increased production of inflammatory cytokines IL-6 and TNFα." (PMID 32455939, 2020). "The first, 5 days of infection showed peak levels of IL-1RA, MCP-1, MIP-1β and TNF-α; the second 5 days had peak levels of GM-CSF, IL-1β, IL-6, IL-8, IL-9, IP-10 and MIP-1α; VEGF peaked at 11–15 days." (PMID 32264832, 2020). "In response to LPAI infection, pathways enriched in the ileum included metabolism, JAK/STAT signalling, IL6 signalling and regulation of T cells." (PMID 32050986, 2020). "Pulmonary concentrations of pro-inflammatory cytokines and chemokines (e.g. IL-6, IFNγ, and CCL2) broadly increased in response to infection at 3 and 9 dpi, and then declined following control of viral replication at 14 dpi." (PMID 32645119, 2020). "The genes, Ccl2, Ccl20, Csf1, Cx3cl1, Cxcl1, Cxcl3, Il6, Birc3, Map3k8, Nos2, Nfkb2, Tnfrsf1b, and Vcam1, played core roles in a PPI network, and interacted closely with other ones in the infection." (PMID 33042984, 2020). "In general, H3N2 and H5N1 infection induced IFN-α, TNF-α, MCP-1 (CCL-2), IL-1β, and IL-6 responses in ANP32B+/+ mice were reduced in ANP32B−/− mice, particularly 3 days post infection." (PMID 32231671, 2020). "The pro-inflammatory molecules; IL-6, IL-8, RANTES and MCP-1, which recruit and activate other cell types to the infection site and amplify the inflammatory cascades, were augmented by all three stains of ZIKV in astrocytes." (PMID 30735502, 2019). "As expected, several cytokines including TNF-α, IL-1β, IL-6, IL-8, and IFN-γ were significantly increased in a time-dependent manner upon virulent Mtb strain H37Rv infection detected by qRT-PCR in hMDMs." (PMID 30717477, 2019). "Proinflammatory cytokines including IL-1β, IL-6, IL-8, and TNF-α are upregulated and peak at 48 hpi in primary PAMs during infection." (PMID 31363150, 2019). "At 24 h post-infection, the ESRD group showed significantly lower levels of IL-1Ra, IL-6, IL-8, IL-10, IL-12p40, TNF-α, VEGF, MCP-1, and MIP-1b as compared to the control group." (PMID 31875015, 2019). "Similar to infection in BMDMs, lungs from coinfected WT mice showed increased production of IL-1β, TNF-α, and IL-6 compared to PR8 or S. p. single infection of WT mice." (PMID 30794604, 2019). "Interleukin 6 (IL-6), gamma interferon (IFN-γ), KC (CXCL1), and MCP-1 were consistent markers of inflammation during infection." (PMID 31597722, 2019). "TLR8 inhibition also strongly reduced TNF and IL-6 induction by GBS and S. aureus, and reduced IL-10 production at the late time point, while TLR8-inhibition increased the level of IL-8 after 22 h of infection with the highest dose of bacteria." (PMID 31214180, 2019). "Compared with the mice in the CTRL group, those in the CR-infection and QUE groups showed significantly elevated IL-10, IL-17, IL-6, and TNF-α levels (all p < 0.05)." (PMID 31156598, 2019). "In contrast to the findings at 48 hpi, most of the inflammatory cytokines, including IL-6 and IFN-γ, were suppressed in the lungs at 18 hpi, consistent with the immune suppressive phase of the infection." (PMID 30642901, 2019). "These proteases affect also the integrity of the cytokines IL-6, IL-8, IL-12, and TNF-α, which are produced in response to the infection." (PMID 31049022, 2019).
infection (continued). "Consistently, mRNA levels of IFNB1, ISG56, CXCL10, and IL6 genes induced by HCMV-ΔUL42 were significantly higher than those induced by HCMV-WT at 6, 12, and 24 hr post-infection in HFFs, human primary monocyte-derived dendritic cells and macrophages." (PMID 31107917, 2019). "Infection and local tissue injury generate the release of proinflammatory cytokines including TNF-α and IL-6, which contribute to increased systemic inflammatory responses." (PMID 31885498, 2019). "Moreover, pathways such as “IL-10 signaling,” “IL-6 signaling,” “NF-kB signaling,” “Acute phase response signaling,” and “Differential regulation of cytokine production in macrophages and T helper cells by IL-17A and IL-17F” showed strong regulation of immunity-related genes during early infection." (PMID 31969876, 2019). "SCs responded to infection with increased expression of mRNAs for IFNβ, IFNλ, IFIT-1, Mx1, NLRP3, IL-23A, IL-6 and TNFα." (PMID 31289325, 2019). "Interestingly, IN immunization with these recombinant proteins followed by infection with the mutant strain resulted in a strong decrease in the release of IL-6 in the kidney, indicating that curli hide these fimbriae, which could be an immune response evasion strategy of UPEC." (PMID 31551993, 2019). "In contrast, expression of IFN‐γ and IL‐6 in some tissues was increased at 48 hpi following both GD and F48E9 infection, compared to that of the control." (PMID 30070070, 2019). "As Plcb2−/− mice had significantly higher mRNA levels of Tnf, Il6 and Il12 and little changed viral loads compared with wild-type mice after CVA16 infection, we next monitored the survival and histopathological pathogenesis of mice challenged with CVA16." (PMID 30765691, 2019). "In side-by-side infections of chickens and ducks with two Eurasian lineage HPAI H5N1 viruses, IL-6 and other pro-inflammatory cytokines were more potently induced in chickens and correlated with higher mortality." (PMID 30634569, 2019). "Both the HEV experimental infection and increased dietary Met content contributed to a significant (P < 0.001) decrease in the blood percentage of CD4+ cells, synthesizing IL-6 in response to mitogenic stimulation under in vitro conditions." (PMID 31675966, 2019). "Tc infection increased plasma levels of IL-1β as well as other HPA axis-activating cytokines such as TNF-α, IFN-γ, or IL-6." (PMID 31998227, 2019). "At 24 h post-infection, the mRNA level of TNF-α, IL-1β, and IL-6 were measured by relative quantitative RT-PCR normalized against peptidylprolyl isomerase A (PPIA), a molecule that has been previously used for internal control." (PMID 31561412, 2019). "Other markers that were upregulated during the early active infection phase included IFN-γ, IL1-RA, IL-6, IL-10, IL-15, and IL-18; all of which have been reported in cases of human disease." (PMID 31557262, 2019). "Infection of mice with S. aureus-induced an early inflammatory cytokine response with high levels of IL-1α, IL-1β, IFN-β, TNF-α, IL-6, IL-12p70, IL-27, and IFN-γ in the spleen detected for up to 12 h pi compared to PBS-treated mice." (PMID 31134074, 2019). "This process ensues the development of a cytokine cascade, some of them with protective roles, including IL-12, IL-13, IL-6, CXLL2, CCL7, CCL2, TNF-α, and consequent neutrophils recall in the site of infection." (PMID 31508399, 2019). "The inflammatory kinetics of serum in mice at 1, 3, 7 and 11 days after infection by SL1344, CVCC541, and CMCC50115 showed that SL1344 induced significantly high levels of IL-1β, IL-6 and TNFα at 1 and 3 days." (PMID 30898022, 2019). "To study the influence of B1R/B2R on the inflammatory response at the primary site of infection, we measured cytokine (tumor necrosis factor (TNF) α, interleukin (IL)-1β, and IL-6) and chemokine (CXCL1, CXCL2, and CCL2) levels in whole lung homogenates." (PMID 30874974, 2019).
infection (continued). "It is worth mentioning the slight reduction of IL-6 in the treated animals and especially in those receiving AHCC®, since IL-6 is a biomarker of the infection severity (P = 0.059)." (PMID 31484389, 2019). "Infection of IL-10−/− mice with C. jejuni is characterized by increased levels of pro-inflammatory cytokines (TNF-α, IL-1β, IL-6, IFN-γ and IL-22) and infiltration of inflammatory cells in the colon." (PMID 31427597, 2019). "As expected, a strong proinflammatory response, demonstrated by drastic cytokine expression, including IL-6 and TNF-α, was observed early upon infection." (PMID 31998663, 2019). "During the course of an infection, the excessive circulating ranges of TNF-α, IL-1β, and IL-6 indicate a rapid array of host responses, such as fever and leukocyte chemotaxis." (PMID 30949497, 2019). "After infection, when compared with the lean group, the contents of TNF-α, IL-1β, IL-6, IL-8, resistin, and leptin in the lean-E." (PMID 31085802, 2019). "For the hub response genes of E. coioides, IL6 and IL1B were induced, while CELA2, TRY, CPA1, CPA2, and CPB1 were repressed throughout the infection process." (PMID 31130962, 2019). "Macrophages in BALF remained markedly high during infection, with concomitant increase in pro-inflammatory cytokines (TNF-α, IL-1β, IFN-γ, and IL-6), compared HAdV-3 infection." (PMID 30626350, 2019). "The other cytokine such as IL-6, TNFα, response to early febrile and defervescence phases of DENV-infection varied significantly and even led to contradictory conclusions." (PMID 31877138, 2019). "Through the combined effects of IL-6 and TGF-β, CD4+ T cells differentiate into Th17 cells and secrete IL-17A, which plays a key role in host defense against infection." (PMID 31297140, 2019). "Serum concentrations of IFN-γ and IL-6 followed the same profile observed for TNF-α concentration, and MCP-1 levels were detected only on the third day after infection." (PMID 31687410, 2019). "The pro-inflammatory cytokines IL-6 and IL-1β were strongly induced post-APEC O1-GFP and slightly higher post-APEC O2-GFP infection in macrophages." (PMID 31998322, 2019). "Treatment of WT‐derived BMMCs led to significantly elevated levels of IL‐6, TNF‐α, KC, MIP‐2 and CRAMP in KitW-sh/W-sh mice upon infection." (PMID 30729611, 2019). "In the current study, the release of the inflammatory cytokines IL-6, TNF-α, IL-1β, and IL-12 in the serum of the TG mice was reduced compared with that of the WT mice after infection with S. Typhimurium or administration with LPS." (PMID 31379864, 2019). "The TLR3 signal also causes an upregulation of TLR2, which participates in the expression of IL1β, IL6, CCL2, and CCL5 genes by primary C57BL/6 astrocytes following a TMEV-BeAn infection." (PMID 30669615, 2019). "IL-6, IFN-γ, MIG, IL-17, and IL-9 are important inflammatory cytokines in the anti-infection immune response and were all increased in the blood of patients with AE-IPF in our cohort." (PMID 30718973, 2019). "Overall, these results indicate that RIG-I signaling is dispensable for triggering type 1 IFNs and IL-6, and in control of virus replication following ZIKV NS4B-C100S infection in macrophages." (PMID 31815005, 2019). "We observed that ZIKV increased the secretion of pro-inflammatory components, especially IL-6 and MCP-1 since initial times of infection, in agreement with a previous work that described an inflammatory profile of astrocyte and microglia during ZIKV infection." (PMID 31882804, 2019). "After overnight infection, all cell types produced comparable amounts of NF-κB-dependent cytokines, namely TNF IL-6 or IL-12p40, whatever the rBCG strain used for stimulation." (PMID 31921172, 2019). "Among its target genes, we observed increased expression of IL6, IL8, CCL5 and CXCL10 at different time points post infection." (PMID 31575039, 2019).
infection (continued). "To examine the pHAECs response to infection by the two viruses, we determined the mRNA levels for RSV M as well as those of IL-6, CX3CL1, CCL7 (MCP-3), Muc5AC, and Muc5B." (PMID 31330970, 2019). "The use of IL10-targeting siRNA revealed that IL10 inhibited the production of IL1B, IL6, tumour necrosis factor (TNF) and interferon gamma (IFNG) during infection of bMDM with the M. bovis strain G18." (PMID 31527895, 2019). "CRP and SAP are mainly expressed in hepatocytes in response to interleukin-6 (IL-6), whereas PTX3 is produced by different cell types at sites of local infection and inflammation." (PMID 31744201, 2019). "In Mtb-infected/Fe-supplemented rabbits, expression of IFNG, TNFA, and IL1B was significantly down-regulated, whereas expression of IL6 and SMAD6 was up-regulated, compared to placebo-treated animals, at 4 weeks post-infection." (PMID 31382404, 2019). "Organs were harvested at day 3 and 5 of infection and total RNA was isolated and amplified for the mRNA of the housekeeping gene, HPRT, and the cytokines TNF, IL-6, IL-12 and IL-10." (PMID 31242184, 2019). "At later times in the acute infection phase, the amounts of IFN-γ fell while IL-6, IL-10, and IL-12 became the predominant cytokines in PMNd-Br mice." (PMID 30804100, 2019). "The protein levels of IL-5, IL-6, IFNγ, G-CSF, and MCP-1 (CXCL2) were significantly higher in ZBP1−/− mice compared to the WT mice at day 4 after infection." (PMID 31572318, 2019). "Other cytokines such as G-CSF, IL-6, and TNF-α were apparently increased by FCPLJ treatment especially on day 3 post infection." (PMID 30744623, 2019). "Strikingly, we observed that three major inflammatory cytokines (IL-6, TNF-α, and IL-1β) were produced less during infection in AIC than in LCC." (PMID 31801841, 2019). "In this study, we first showed that high levels of G-CSF and IL-6, biomarkers for an inflammatory response, are produced in most tissues of PRV-Becker infected mice at early time post-infection." (PMID 31675371, 2019). "Nonetheless, PKR is important for the production of IFN-I, IL6, CCL2, and CXCL10 in primary SJL astrocyte cultures, whereas TLR3 plays only a minor role in the responses to a TMEV-BeAn infection." (PMID 30669615, 2019). "In the lungs isolated after 4 days of infection, combination VLPs groups had significantly lesser levels of pro-inflammatory cytokines IFN-γ and IL-6 than Naïve + Challenge group." (PMID 31246961, 2019). "Cytokines GM-CSF, GRO-α, I-309, IL-1β, IL-6, MCP-1, MCP-2, TNF-α, thrombopoietin, BLC, Flt-3 ligand, HGF, IP-10, MIF, and MIP-3α were elevated by ≥1.5 fold relative to mock infection in both independent biological replicates of the cytokine array." (PMID 31536604, 2019). "Under inflammatory conditions, hepcidin is transcriptionally induced by IL-6/STAT3 signaling and promotes hypoferremia, an innate immune response to infection." (PMID 31295319, 2019). "Inflammation is a complex biological response to harmful stimuli, tissue injury, or infection and produced a number of proinflammatory mediators, such as TNF-α and IL-6." (PMID 31886241, 2019). "Compared to ZIKV/Cambodia, the experimental infection of hiNPCs with ZIKV/Brazil resulted in a diminished induction of ISGs and lower induction of several cytokines (IFN-α, IL-1α/β, IL-6, IL-8, and IL-15), consequently favoring virus replication." (PMID 31474994, 2019). "Similar to WT mice, in the CNS of Rag1−/− mice IFN-α1, IFN-β, TNF, IL-1α, IL-1β, IL-6, and IFN-γ mRNA levels increased following i.c. infection with ZIKV, and IL-2, IL-3, IL-4, and IL-5 mRNA was not detectable (data not shown)." (PMID 31511023, 2019). "Our results showed that Hypr infection of HBCA induced increased production of numerous cytokines/chemokines—particularly CCL5 (RANTES), CXCL10, IL-6, and IL-8, which confirmed our previous findings." (PMID 31699097, 2019).